CD4 (CD4 molecule)
Diseases named in the same sentence as CD4 in open-access papers (continued):
Sharing a sentence is not in itself a finding about the gene and the disease.
infection (continued). "Nevertheless, in contrast to CD8+ T-cells, which have been inversely correlated with disease severity, asymptomatic infection may induce lower frequencies of SARS-CoV-2-specific CD4+ T-cells compared to mild disease." (PMID 39340081, 2024). "One cohort did not demonstrate any association between multiple variant infection and either viral load or CD4+ T cell decline." (PMID 39471873, 2024). "A study by Malim’s group demonstrated how HIV-1 utilizes virion-delivered Vpr to induce wide-ranging transcriptional alterations in primary CD4+ T cells as early as 4.5 h post-infection, clearly anticipating interferon-stimulated gene (ISG)-dependent expression changes by about 8 h." (PMID 38543785, 2024). "However, the infection of microglial cells in vivo through cell-to-cell fusion with infiltrating infected CD4+ T-cells is yet to be demonstrated." (PMID 38713307, 2024). "Similarly, when analyzing cytokine production upon PMA/Ionomycin stimulation, a steady increase in IFN-g+ CD4+ T cells from 1-4 weeks post-infection, and only a minor shift in IL-4+ CD4+ T cells around 2 weeks post-infection was detected." (PMID 38799456, 2024). "Infiltrating neutrophils engulf mycobacteria and may contribute to early protection, directly or indirectly by interacting with CD4+ T cells, but excessive recruitment of neutrophils correlates with lung pathology in both human and mouse Mav infection." (PMID 39737195, 2024). "In a longitudinal analysis of the most abundant spike haplotypes in each person, rapid fluctuations in frequency observed in most PWH with CD4 counts <200 cells/μL contrasted sharply with the persistence of a single predominant haplotype throughout the course of infection in every PWOH." (PMID 38313289, 2024). "Thus, it is clear that CD4 T cells contribute to resolution of B. microti primary infection in the C57BL6 mouse background." (PMID 38392861, 2024). "CD4+ T cells play a significant role in the production of antibodies during infection." (PMID 39057781, 2024). "This bias may have resulted in our lack of identification of host factors previously determined to be required for HIV-1NL4-3 infection, such as CD4 or CXCR4." (PMID 38835488, 2024). "Considering that CD4 surface expression levels on CD4+ T-cells and microglia are likely to differ between donors, we used 3 different donors and three laboratory strains as a control for infection: two R5 M-tropic virus (Bal and YU-2) and one R5 T-tropic virus (JRCSF)." (PMID 38713307, 2024). "For risk groups associated with a greater probability of multiple variant infection, such as MSM-receptive and PWID, the overall distribution of the daily rate of CD4+ T cell decline remained consistent with risk groups associated with a lower probability of multiple variant infection." (PMID 39471873, 2024). "Interestingly, during chronic HIV infection (40 days post-infection), the therapeutic administration of IFNA2A- or IFNA8-encoding plasmids was ineffective in preventing CD4+ T cell depletion." (PMID 38543729, 2024). "In murine and preclinical animals studies cellular immunity is known to play an essential role in protection against rickettsial infections, with both CD4+ and CD8+ T cell-deficient mice demonstrating increased susceptibility to infection with TG, SFG, and O. tsutsugamushi." (PMID 38567021, 2024). "However, the exact mechanism by which women maintain consistently lower VL than men, despite more activated CD4+ T cells early in infection, has yet to be elucidated." (PMID 39902043, 2024). "Attempts to cure established infections by depletion of CD4 T cells were initially ineffective." (PMID 38611110, 2024). "γδ T cells might be part of the primary response to infection with live bacteria, whereas CD4+ T cells regulate the secondary immune response, which protects against exogenous reinfection or reactivation of endogenous disease." (PMID 38741147, 2024).
infection (continued). "Indeed, the number of eosinophils and other mononuclear phagocytes recruited to the infection site increases after repetitive sand fly bites and depends on CD4+ T cells signalling in response to specific salivary proteins." (PMID 38198296, 2024). "As shown from our data, neutralizing antibodies and CD4 T cell levels towards most strains correlated among previously non-infected individuals and low levels were independent indicators for subsequent breakthrough infection." (PMID 38594497, 2024). "CTLA-4 expression levels on spike-specific CD4+ and CD8+ T cells in infection-naive patients were numerically higher than in convalescent patients with statistically significant differences observed for spike-specific CD4+ and CD8+ T cells towards Omicron BA.4/5." (PMID 38326340, 2024). "Moreover, this is largely reliant on CD4+ T cells, which trigger the release of potent cytokines to combat the infection." (PMID 38809023, 2024). "However, to our knowledge, this study is the first example where a population of memory CD4 T cells having such a dramatic impact on viral persistence shows apparent epitope-selection during natural infection." (PMID 38236791, 2024). "Moreover, the infection rate of E. bieneusi in persons with <200 (25.97%) CD4+ T cells was higher than that in those with >200 CD4+ T cells (21.76%)." (PMID 38345479, 2024). "Moreover, the protection conferred by antibodies is highly dependent on CD4+ T cell-mediated adaptive changes that take place in the local genital tract tissues during the primary infection." (PMID 38371301, 2024). "Next, we dissected the effects of RACK1 on CD4+ T cell responses after P. yoelii 17XNL infection." (PMID 39024388, 2024). "Infection with IAV has also been shown to induce the formation in the lungs of inducible bronchus-associated lymphoid tissues (iBALT), lymphoid organizations that include primarily CD4 cells together with B cells." (PMID 38645169, 2024). "Males, older age, low CD4 counts and detectable HIV-VL may be associated with lesser symptoms among PLWH with the Omicron variant infection." (PMID 39127636, 2024). "However, HIV-1 establishes new infections at mucosal surfaces and then in neighboring draining lymph nodes, which are both heavily populated with CD4+ T cells and myeloid cells including macrophages." (PMID 38400063, 2024). "Similarly, an increase in effector/memory CD4+ T cells was observed in mice that received 1x or 2x infections prior to an IN challenge." (PMID 38576622, 2024). "Locally activated CD4+ and CD8+ T cells (with CD4+ T cells predominating in early infection) mediate bacterial clearance primarily through the production of IFN-γ, which stimulates macrophages to internalize and degrade treponemes and triggers an inflammatory cascade." (PMID 39770782, 2024). "Additionally, our findings underscored that the highest infection rates are observed in WLWHIV with low CD4 T-cell counts at baseline." (PMID 38778266, 2024). "Notably, the number of Her2+ cells in the lung was also significantly decreased when the depletion of CD4 cells was initiated 10 dpi, supporting the contribution of CD4 cells later during the infection." (PMID 38645169, 2024). "However, examination of the proportion of Foxp3 expressing CD4 cells in LCMV infected animals showed that both genotypes exhibited a decrease in Tregs following infection." (PMID 38512979, 2024). "Similarly, C3H/HeN mice immunized with recombinant YbgF from R. heilongjiangensis (the causative agent of Far-Eastern Spotted Fever; FESF) results in a CD4+ T cell response that limits the bacterial burden upon infection with homologous bacteria." (PMID 38567021, 2024). "The virus multiplies within cells, generating new viral proteins, with MHC class I presenting antigens to T CD8+ cells for targeted cell destruction and MHC class II activating T CD4+ cells influencing immune responses through cytokines, controlling infection and inhibiting viral replication." (PMID 39104592, 2024).
infection (continued). "Additionally, IL-27 signaling promoted survival of virus-specific CD4 T cells and viral control during early infection." (PMID 38966644, 2024). "Consequently, RACK1 in CD4+ T cells contributes significantly to germinal center formation, parasite-specific IgG production, and host resistance to the infection." (PMID 39024388, 2024). "There was a significantly reduced percentage of CD4+ T cells-expressing TIGIT following infection." (PMID 39109867, 2024). "The neuroinflammatory effects, which were predominantly noted in animals infected with HIV-1CH040, may be attributed to the dual infection of CD4+ T cells and macrophages, which in the brain can more readily increase neuroinflammatory responses." (PMID 38945996, 2024). "Of note, a recent clinical trial provided evidence that infusion of ex vivo CCR5-edited CD4+ T cells could delay viral rebound and that post-rebound control of infection was possible in 1 of 9 CCR5wt/wt PLWH." (PMID 39459922, 2024). "Collectively, these results demonstrated that primary NMI infection induced a comparable level of protection against the high dose NMI reinfection in WT and CD4+ T cell deficient mice, and a partial protection in B cell deficient, CD8+ T cell deficient and T cell deficient mice." (PMID 39469719, 2024). "Within the pre-infection immune cell population, 17.3 ± 1.3% were CD4+ T cells, 21.5 ± 3.1% were CD8+ T cells, 1.8 ± 0.3% were NCR1+ NK cells, 12.8 ± 2.3% were IgM+ B cells, 5.4 ± 0.7% were IgG1+ B cells, 5.9 ± 0.6% were CD14+ monocytes, and 4.9 ± 0.9% of immune cells expressed cell surface CD25." (PMID 39459849, 2024). "In addition, CD8+ T cell exhaustion has been strongly associated with impaired CD4+ T cell help, a crucial process by which CD4+T cells support the differentiation and maintenance of robust CD8+ memory T cell responses during infection." (PMID 39399649, 2024). "This segregation was largely driven by increased frequencies of plasmacytoid dendritic cells (pDC, cluster 43), CD45RA+Foxp3+CD4+T cells (resting Tregs, cluster 7), and basophils (cluster 35) as well as decreased frequencies of memory CD4+T cells (clusters 4, 9, and 19) after infection." (PMID 39013877, 2024). "For the lymphocyte population in the brain, the infection rate was ~1.4% (10-fold higher than the myeloid population), which is consistent with the fact that lymphoid cells, especially CD4+ T cells, are primary leukocytes to be infected during acute SIV/HIV infection." (PMID 39283947, 2024). "Infection of various cell types including differentiated monocytic, microglial, and CD4+ T cell lines, as well as primary CD4+ T cells, with HIV-1 induces an upregulation of m6A levels in total cellular RNA through mechanisms that remain unclear." (PMID 38257827, 2024). "The structural proteins appear to be the major targets of CD4+ T cell responses during infection." (PMID 38318179, 2024). "We assessed therefore whether an ELISpot IL-21 assay on CD4+T cells, conducted simultaneously at the same time as serology on samples obtained closest to the time of breakthrough infection, could predict the humoral response." (PMID 39104410, 2024). "Opportunistic infection seen according to the CD4 cell count in blood." (PMID 39050280, 2024). "Our results demonstrated that primary NMI infection induced a comparable level of protection against the high dose NMI reinfection in WT and CD4+ T cell deficient mice, and a partial protection in B cell deficient, CD8+ T cell deficient and T cell deficient mice." (PMID 39469719, 2024). "Double depletion of CD4+ and CD8+ cells was associated with marked weight loss in the early phase after infection, though to a lesser extent than the control group and exhibiting a later recovery, alongside a reduction of the survival rate to approximately 60%." (PMID 39669563, 2024).
infection (continued). "Statistically significant differences were observed among subtypes concerning gender, age, marital status, education, occupation, infection route, infection time, pre-treatment CD4 T cell counts, pre-treatment Viral load, clinical stage, and drug resistance before treatment (p < 0.05)." (PMID 38994006, 2024). "In addition to providing help with B cell production of antibodies, CD4+ T cells release proinflammatory effector molecules, such as IFNγ and TNFα, during infection." (PMID 38567021, 2024). "The analysis revealed that infection time, HIV-1 subtype, infection route, gender, age, pre-treatment CD4+T lymphocyte count, clinical stage, treatment regimen, duration time for initiated treatment, and treatment time significantly impacted post-treatment CD4+T lymphocyte recovery." (PMID 38994006, 2024). "Also, our results showed that pp65 was the immunodominant target for CD4+ in remote infection, whereas gB was the immunodominant target for CD8+ in primary infection." (PMID 39336935, 2024). "Analyses for each treatment group were performed independently using multivariate regression models with HIV-1 DNA levels as the dependent variable and other factors, specifically nadir CD4, pre-infection CD4, baseline CD4 counts and peak viral load, as the independent predictor variables." (PMID 38947072, 2024). "As expected, baboon CD4 cells were more permissive to infection, even at early passages." (PMID 39006742, 2024). "HIV entry from the periphery into the CNS can occur within less than two weeks of infection, via cell free virus, through infected CD4+ T cells, or infected monocytes that migrate to the CNS and differentiate into macrophages, all of which allow HIV to disseminate into the CNS." (PMID 38945996, 2024). "Importantly though, if CD4+ T cells were depleted after vaccination but prior to infection, then significant protection was retained." (PMID 38980038, 2024). "Furthermore, the samples collected later in infection, when cells were infected through either direct local transmission or through systemic seeding, also showed that vRNA+ cells were consistently only CD4+ T cells." (PMID 39641272, 2024). "Indeed, using adoptive transfers, Ballesteros-Tato and colleagues also noted that some CD4+FoxP3- cells upregulated FoxP3 after infection." (PMID 39319261, 2024). "Indeed, even NK cells and CD4+ T cells will become important IL-10 producers in the later stages of the infection as a consequence of persistent and extensive activation." (PMID 39359727, 2024). "The frequency and absolute numbers of multiple immune cell types, including B cells, interstitial and alveolar macrophages, neutrophils, CD8 T cells, CD4 T cells, monocytes and eosinophils were analyzed by ow cytometry at baseline (day 0) and days 1, 3, and 5 post-infection." (PMID 39149485, 2024). "The mechanisms of CMV persistence in the salivary glands upon infection in adults have been extensively studied using a mouse model, and it has been suggested that targeting protective CD4 T-cell epitopes by vaccination could represent an efficient strategy." (PMID 39134803, 2024). "Although it was previously assumed that T cells were primed in the spleen and migrated to the liver to combat the infection, recent studies have shown that parasite-specific CD4+ T cells may be primed in other tissues and are sufficient to confer immunity." (PMID 38881737, 2024). "Collectively, the findings indicate that immunization with M. kansasii not only induces CD4+ multifunctional T cell responses similar to BCG in the lung even after infection with Mtb but can also generate multifunctional Th1 CD4+ T cells that outperform BCG in the spleen." (PMID 38980025, 2024). "In addition, activated CD4+ T cells were significantly more abundant at the site of infection, where they represented up to 15% of all nasopharyngeal-resident T cells at day 10 after inoculation." (PMID 38898278, 2024).
infection (continued). "Additionally, three relevant factors (different modes of infection, baseline CD4 + T cell counts, CD4 + T cell counts at treatment initiation) were included in the multivariable Cox proportional hazards regression model, totaling five factors." (PMID 38869754, 2024). "CCR5 is expressed on memory CD4+ T cells, macrophages, microglia, and dendritic cells, and is the co-receptor used by “transmitted/founder” (T/F) viruses passed from one individual to another to establish initial infection." (PMID 39205255, 2024). "MCMV induces a robust and diverse CD4 T cell response early during infection in mice, with persistent replication in the salivary gland (SG) for several months, and CD4 T cells are absolutely critical for ultimately resolving this extended replication prior to “whole host latency” being established." (PMID 38236791, 2024). "However, this was analyzed at 3 weeks of infection, a time where IL-10 is highly produced by conventional CD4 T memory cells and M09 cells are far from peak levels, and IL-10 suppresses MHC-Il during MCMV infection." (PMID 38236791, 2024). "As regards the four donors at the late phase of infection, N-specific CD107a+ CD4+ T-cells with cytotoxic granules may have a trend to be maintained longer than N-specific CD107a+ CD8+ T-cells (compare right to left panel)." (PMID 38543812, 2024). "Also, macrophages and CD4+ T cells can be found in smaller amounts, during the acute phase of the infection." (PMID 38785783, 2024). "This highlights the paradigm that Th1 CD4 T cells are required to resolve infections with most intracellular bacterial pathogens, however, they do not explain all of the protective mechanisms which occur through unknown mechanisms." (PMID 38567021, 2024). "The study involved infecting a humanized mouse model with HIV to test whether the infusion of irradiated SupT1 cells could act as a decoy target for the HIV virus to prevent infection of primary CD4+ T cells." (PMID 38664792, 2024). "LP was based on the consensus definition and, as such, may be overestimated due to a transient decrease of the CD4 count upon seroconversion period and in the early stage of infection." (PMID 38500732, 2024). "HTLV-1 is an enveloped single stranded RNA human deltaretrovirus that causes lifelong infection of CD4+ and CD8+ T-cells, monocytes, and other lymphoid and non-lymphoid cells via the ubiquitous glucose transporter-1 (GLUT1) and neuropilin." (PMID 39228892, 2024). "Thus, TLR2−/− DCs infected with L. braziliensis were more competent at priming naïve CD4+ T cells, which was associated with increased IFN-γ production and greater resistance to infection." (PMID 38474410, 2024). "Overall, our findings showed that heterologous infection or immunization priming of CD4+ T cells induced large numbers of lung TRM following PR8-HA-GP61-80 rechallenge, with a Th1-like or Tfh-like subset distribution that was dependent on the primary immunization or infection challenge." (PMID 39283916, 2024). "Moreover, it has recently been demonstrated that a small fraction of deeply latent genetically intact proviruses are archived in CD4 T cells during the very first weeks of infection." (PMID 38947072, 2024). "Furthermore, Sig1R was identified as a key modulator in HIV-1/METH pathobiology in CD4+ T cell activation and infection." (PMID 39175523, 2024). "The transmigration of infected CD4+ T cells and macrophages across a highly permeable BBB, especially in the initial stages of infection, can lead to the infection of CNS cells: CD4+ T cells and macrophages can persist in the CNS or propagate the infection to CNS cells (ex vivo study)." (PMID 39685490, 2024). "Also, the population of Th17 (CD4+RORgt+) cells, which increased by infection, showed a decreasing due to C1 treatment." (PMID 39081865, 2024).